COL17A1 (collagen type XVII alpha 1 chain)
Diseases named in the same sentence as COL17A1 in open-access papers (continued):
Sharing a sentence is not in itself a finding about the gene and the disease.
tumor (62 papers, 2012 to 2026). "One study identified alterations in the hemidesmosomal proteins β4 and COL17A1 and a change in their localisation from cell membrane to cytoplasm, which was associated with tumour progression within oral tissues." (PMID 37173998, 2023). "The patient data indicated that high COL17A1 expression was associated with low-proliferation tumors, increased tumor-free and overall survival times." (PMID 34293053, 2021). "We investigated whether cancer type influences the risk of developing ICI-induced BP and whether COL17A1 mutations or dysregulation in tumor tissue contributes to disease-specific variation." (PMID 41658267, 2026). "Quantification of the tumors showed that depletion of COL17A1 by shRNA#1 and shRNA#3 reduced tumor weight by 52% and 74% and tumor size by 75% and 82%, respectively (P < 0.01)." (PMID 40728119, 2025). "Taken together, these results suggest that the tumor microenvironment stimulates COL17A1 expression." (PMID 40728119, 2025). "COL17A1, a member of the collagen family, exhibits abnormal promoter methylation leading to overexpression in cervical and epithelial cancers, enhancing tumor invasiveness." (PMID 41132793, 2025). "As the dense stromal compartment in PDAC comprises up to 90% of the tumor volume, we sought to clarify the expression pattern of COL17A1 to further differentiate between cancer or stroma origin." (PMID 40728119, 2025). "Upon transduction of the sh‐COL17A1 lentivirus in the xenograft models, tumor growth was significantly blunted, as evidenced by the decreased volume and average weight of sh‐COL17A1 xenograft tumors." (PMID 39143031, 2024). "In pancreatic cancer, COL17A1's impact on in vivo tumor growth varies depending on the tumor microenvironment." (PMID 39143031, 2024). "Computational algorithm analyses have shown that COL17A1 is closely related to the tumor microenvironment, prognosis, and chemosensitivity in pancancer by acting as an immune‐related factor." (PMID 39143031, 2024). "The clinical correlation of key genes was analyzed, and the results showed that the expression of ECT2 and COL17A1 was significantly correlated with tumor grade (P < 0.05)." (PMID 35722628, 2022). "The expression of COL8A1, COL10A1 and COL17A1 were found to be significantly elevated in many different tumor types 30-34 and they were all tumor-related genes." (PMID 33753985, 2021). "This is in accordance with the results of public database analysis, and immunohistochemical results show that the COL17A1 protein level was enhanced in tumor tissues in comparison with adjacent normal tissues at a significant level (p < 0.0001)." (PMID 33381179, 2020). "The mRNA levels of expression of COL17A1 were upregulated in the tumor tissues when compared with the normal pancreatic tissue." (PMID 33381179, 2020). "CCK-8, wound healing, and transwell assays suggested that COL17A1 knockdown markedly inhibited tumor proliferation and invasion in PDAC cells, and cells with COL17A1 overexpression had a prominently higher proliferative and invasive capacity." (PMID 33381179, 2020). "The downregulated MCOLN3 and SLC25A45 with HR < 1 were considered as tumor suppressors, whereas the upregulated COL17A1, CEP55, KLK10, MET, ITGB6, ANKRD22, and ARNTL2 with HR > 1 were regarded as oncogenes." (PMID 31612115, 2019). "This implies that aberrant epigenetic control is a key driver of COL17A1 gene misexpression and tumor cell invasion." (PMID 27891193, 2016). "A recent study using an inducible lineage-tracing system in CRC organoid xenografts has revealed that dormant LGR5+p27+ cells, anchored at the COL17A1-enriched matrix interface, persist in a drug-tolerant state during chemotherapy and later reinitiate tumor growth." (PMID 41002429, 2025). "Similarly, COL17A1 promotes tumor aggressiveness, as COL17A1 depletion inhibits proliferation, migration, and invasion through modulation of extracellular matrix (ECM) remodeling and chemoresistance pathways." (PMID 40486509, 2025).
tumor (continued). "Similarly, tumors formed by COL17A1-deficient MGH1275 cells were significantly smaller compared with NTC tumors, with a reduction in tumor weight of 79% and 81% and a reduction in size of 73% and 81% for shRNA#1 and shRNA#2, respectively (P < 0.0001)." (PMID 40728119, 2025). "Targeting COL17A1 via upstream TGF-β1 blockade using Tranilast or potentially other compounds such as Galunisertib or Vactosertib may reduce tumor progression and cellular aggressiveness." (PMID 40770187, 2025). "Taken together, these studies reaffirm our bioinformatics-based analysis and suggest that these extracellular matrix genes (CDH3, COL11A1, COL1A1, COL17A1, KRT19, ITGA2, LAMC2, and SULF1) are highly associated with PDAC tumor carcinogenesis and peritoneal metastasis." (PMID 39682235, 2024). "Moreover, the crucial functions of COL17A1 in tumor progression have been established by a lot of documents." (PMID 39143031, 2024). "We, therefore, speculate that COL17A1 works through cell surface receptors to mediate tumor progression as against the function of cell-matrix adhesion molecules in PDAC." (PMID 33381179, 2020). "Instead of acting through fusion protein production it can also could use other mechanism to influence expression of genes important in tumor pathogenesis, in this case, upregulate COL17A1 expression." (PMID 29156757, 2017). "To test this hypothesis, we directly compared the absolute COL17A1 mRNA levels in the five tumor types and the respective matched normal control tissues investigated above." (PMID 27891193, 2016). "For the remaining cancers, we find that the degree of COL17A1 promoter methylation is significantly reduced in the tumor samples (n = 516, n = 435, n = 361, respectively) compared to normal control samples (n = 50, n = 29, n = 41, respectively; p ≤ 0.0002, Mann-Whitney U test)." (PMID 27891193, 2016). "However, the absolute COL17A1 levels vary widely between various tumor types, as well as between various normal tissues." (PMID 27891193, 2016). "Additionally, COL17A1 expression was significantly related to tumor differentiation and TNM stage." (PMID 39143031, 2024). "Moreover, the analysis of independent prognostic and clinical correlations demonstrated that ECT2 and COL17A1 could not only be independent prognostic factors of PC but also positively correlated with tumor grade." (PMID 35722628, 2022). "Moreover, these cells increased in the phosphorylation of PP2A, and subsequent activation of STAT3 at S727 and the expression of Col17a1, suggesting that the suspension survival pathway is a general characteristic in enriched TICs derived from a variety of tumours." (PMID 27306323, 2016). "PSMB8 affects neuroinflammation by regulating the activity of immunoproteasome, while COL17A1 and BICC1 promote the progression of PNI in tumor cells by regulating matrix homeostasis and ECM." (PMID 41132793, 2025). "Eleven potential tumor targets were identified, including CEACAM5, TMPRSS4, COL17A1, CLDN18, and AQP5." (PMID 40379788, 2025). "Interrogating the single-cell RNA sequencing (scRNA-seq) Atlas database, which includes 10 functionally distinct clusters of both tumor and normal samples, we observed mutually exclusive expressions patterns of L1CAM and COL17A1." (PMID 40770187, 2025). "Under chemotherapeutic stress, downregulation or disruption of COL17A1 leads to the activation of FAK phosphorylation and subsequent nuclear translocation of YAP, which promotes cell cycle re-entry and tumor regrowth." (PMID 41002429, 2025). "The secretion of COL17A1 and MMP2 by these cells enhances their migratory capabilities and contributes to the formation of a fibrotic stroma that facilitates tumor progression." (PMID 40770187, 2025). "Given the significant roles of USP22 and COL17A1 in tumor immune response, future work is required to explore the precise functions of the USP22/COL17A1 axis in the immune response of LUAD." (PMID 39143031, 2024).
tumor (continued). "The interaction between tumor cells and CAF1 cells involves ligand–receptor pairs such as the COL17A1/a11b1 complex, which collectively promote the conversion of pEMT tumor cells to CAF1‐like cells." (PMID 38229179, 2024). "COL17A1, ITGA10 and MMP7 showed high intertumoral heterogeneity between tumor tissues and adjacent tissues." (PMID 36936416, 2023). "We found that in MAGEA4+ tumor cells of SCCIS, the stem cell marker COL17A1 and the proliferation marker PCNA were significantly increased compared with the adjacent tissues." (PMID 38099574, 2023). "Considering its potential utility as an indicator for malignancies of SCCIS tumor cells, we performed IF co-localization of COL17A1, PCNA, and MAGEA4 in SCCIS tissues to investigate stemness and proliferative state of tumor cells." (PMID 38099574, 2023). "Only one collagen gene, COL17A1 (log2 fold change = −8.43), was found to be upregulated in the HCC tumor." (PMID 33995488, 2021). "Among these, COL17A1, ITGB6, LAMC2, and S100P were upregulated in tumor tissues, whereas only CHGA was downregulated." (PMID 33015155, 2020). "The presence of both tumor basal and TSK cells along the leading edge was further supported by immunohistochemical (IHC) staining for COL17A1, a shared tumor basal and TSK marker." (PMID 32579974, 2020). "The mRNA expression levels of COL17A1, CEP55, KLK10, MET, ITGB6, ANKRD22, and ARNTL2 were significantly increased in PAAD tumor tissue." (PMID 31612115, 2019). "Several genes within the S100 family were increased in tumor cells including a tumor-enriched cluster expressing S100A2 together with KRT15 and COL17A1 which are notable as markers of a quiescent stem/progenitor cell population in the most basal layer of the human esophagus." (PMID 36253784, 2022). "The results showed that, regardless of the chip or protein levels, VPS28, HSF1, and PUF60 showed higher expression in tumour tissues than in normal tissues, while COL17A1 and SMOC1 showed significantly higher expression in the adjacent tissues compared with the tumour tissues." (PMID 32964046, 2020). "The metastatic propensity signature (high COL17A1/PSMB8, low CTRC) suggests: PNI facilitation via collagen remodeling (COL17A1), immune-evasion priming through proteasomal antigen processing (PSMB8),protective trypsin depletion in tumor microenvironment (CTRC)." (PMID 41132793, 2025). "Moreover, the BC subtype transcriptome analysis indicates that the original donor BC tumor tissue expresses only a few genes related to the luminal/smooth muscle subtype (GATA3/DES), while the PDX cell line differentiated into a basal subtype (KRT5/6A and COL17A1)." (PMID 40801146, 2025). "All targets, except COL17A1, showed significantly higher expression in PDAC tissue compared to healthy pancreatic, CP, and duodenal tissue (p < 0.001), as well as in tumor-positive versus tumor-negative lymph nodes." (PMID 40379788, 2025).
cancer (36 papers, 2016 to 2026). A tumor composed of atypical neoplastic, often pleomorphic cells that invade other tissues. "Using TriNetX, systematic review, and bioinformatics datasets, we comprehensively assessed the associations of ICI-induced BP with different malignancy types as well as COL17A1 gene expression, mutation frequency, and immune correlations across cancers." (PMID 41658267, 2026). "Most interestingly, knockdown of Col17a1 reduced suspension survival in enriched TICs and in bulk cancer cells expressing S727E point-mutated STAT3." (PMID 27306323, 2016). "COL17A1 upregulation was associated with poor prognosis in these cancers." (PMID 31612115, 2019). "COL17A1 encodes the α chain of type XVII collagen and promotes cell proliferation in cancer tissues." (PMID 40092988, 2025). "Together, these findings highlight that the expression of COL17A1 in PDAC cancer cells is enhanced by human CAFs in vitro and murine stroma in vivo, highlighting the role of cancer–stroma cross-talk in regulating COL17A1." (PMID 40728119, 2025). "Given that COL17A1 and ITGβ4 play crucial roles in the adhesion process in cancer, they were selected for further detailed inquiry in OC." (PMID 39915800, 2025). "In LUAD, hypomethylation of the COL17A1 promoter is observed, implying the elevated expression of the COL17A1 protein in this cancer." (PMID 39143031, 2024). "Because COL17A1 has been unveiled to be related to cancer cell ferroptosis, we then focused on the exact action of COL17A1 in ferroptosis of A549 and H1975 LUAD cells." (PMID 39143031, 2024). "Using the TIMER2.0 website for systematical analysis of COL17A1 in human cancer, we observed its differential expression in tumors versus matched normal tissues, suggesting the dysregulation of COL17A1 in pancancer." (PMID 39143031, 2024). "Among these modulators, COL17A1 possesses critical activity in the early stages of cancer development." (PMID 39143031, 2024). "In a recent study, COL17A1-knockout (KO) CRC organoids were generated to investigate the role of type XVII collagen in the maintenance of cancer stem cells (CSC) dormancy." (PMID 37803411, 2023). "The cell cycle, proteasome, and pathways in cancer were enriched in the high-COL17A1 and ECT2 groups." (PMID 35722628, 2022). "P25 TRAMP CRIPSCs also had upregulated genes related to cancer development and drug resistance, such as Aldh3a1, Ly6d, Il33, Dsg3, and Col17a1." (PMID 35841025, 2022). "Col17a1 plays an essential role in many malignancies by contributing to cancer cell proliferation and invasion." (PMID 35841025, 2022). "This raises the possibility that the absolute COL17A1 levels are similar in different cancers while the basal COL17A1 levels are high in normal breast tissue and low in other normal epithelia." (PMID 27891193, 2016). "We then demonstrated that overexpression of S727A point-mutated STAT3 reduced Col17a1 expression in TICs, while overexpression of S727E point-mutated STAT3 increased Col17a1 expression in bulk cancer cells." (PMID 27306323, 2016). "Although the incidence of ICI-induced BP significantly differed on the basis of cancer type, COL17A1 mutations or dysregulation do not appear to drive this phenomenon, suggesting alternative immune mechanisms." (PMID 41658267, 2026). "COL17A1 has established critical roles in neoplastic transformation and cancer progression." (PMID 39143031, 2024). "Moreover, dysregulation of COL17A1 has been demonstrated to contribute to protumorigenic processes, with COL17A1 being emerged as either a cancer driver or antitumor factor." (PMID 39143031, 2024). "Additionally, COL17A1 has been shown to modulate cancer phenotypes through the mTORC2 and AKT/mTOR pathways." (PMID 39143031, 2024). "Currently, research on COL17A1 has focused on cancer and skin diseases." (PMID 36936416, 2023). "Studies have shown that COL17A1 is over-expressed in a variety of cancers." (PMID 36936416, 2023). "Our results indicate that COL17A1 assumes an oncogene role in many cancers." (PMID 33381179, 2020).
cancer (continued). "Interestingly, despite the fact that the remaining 8.3% (89/1075) of the tumors had gained extra copies of the COL17A1 locus, their mRNA levels were significantly lower than those in diploid cancers (p = 0.0218)." (PMID 27891193, 2016). "Moreover, the promoter luciferase reporter assay showed that Col17a1 promoter activity was greater in enriched TICs than in bulk cancer cells." (PMID 27306323, 2016). "Thus, the COL17A1 promoter methylation status accurately predicts the direction of the misexpression of collagen XVII in five out of five cancer types." (PMID 27891193, 2016). "A previous study reported in Current Biology highlights the crucial role of COL17A1 in the formation of multilayered epithelial structures, an important event in the early stages of tumorigenesis, suggesting the essential implication of COL17A1 in cancer development." (PMID 39143031, 2024). "In addition, the expression and survival of ECT2 and COL17A1 were analyzed in pan-cancer." (PMID 35722628, 2022). "Given notable recent discoveries in COL17A1 expression in cancers, as well as the role of aberrant collagen XVII ectodomain shedding in squamous cell carcinoma, it appears that collagen XVII may play a particularly important role in epithelial cancer growth and invasiveness." (PMID 32266137, 2020). "For example, AKR1B15, COL17A1, CRABP1, and ITPRID1 were downregulated in BRCA, COAD, and PRAD but upregulated in LUAD, highlighting their cancer type-specific regulatory behavior." (PMID 41439026, 2025). "COL17A1, KRT15, KRT17, S100A2, SFN, which have been shown to assume oncogenic roles in various cancers, were among the highly changed genes and positively correlated with p63 expression." (PMID 38012140, 2023). "Firstly, the biological mechanisms of COL14A1, COL17A1, ITGA10 and MMP7 in IPF and cancer are still unclear." (PMID 36936416, 2023). "The KEGG results showed that the cell cycle, pathways in cancer, and proteasome were greatly enriched in the high-expression group of ECT2 and COL17A1 (P < 0.05)." (PMID 35722628, 2022). "In the current study, knockdown of Col17a1 inhibited suspension survival, tumorigenesis and metastasis in TICs, suggesting Col XVII to be a target for cancer therapy." (PMID 27306323, 2016). "Moreover, only low levels of COL17A1 were detected in CAF-1 cells and were unaltered by the addition of cancer cells." (PMID 40728119, 2025). "We investigated the possibility that the absolute COL17A1 levels are similar in different cancers while the normal COL17A1 levels are high in normal breast tissue and low in other normal epithelia." (PMID 27891193, 2016). "Surprisingly, the most upregulated gene in spheroid culture was Col17a1, which has not been reported to be involved in tumorigenicity and survival ability of cancer cells." (PMID 27306323, 2016). "Given that cancer cell clusters in pLN+ OSCC are ‘TGF‐βI positive’ with enriched EMT functions, we speculate that TGF‐βI is involved in upregulating EMT by inducing the marker genes in these subclusters, such as COL17A1, ITGA6 and CDH13." (PMID 40038875, 2025). "Notably, none of these pairs have been directly associated with TGFβ signaling or EMT, although many of the identified ligands (e.g., LAMC2) or receptors (e.g., CD151, COL17A1, ITGA2, ITGA3, ITGA6, ITGB1, and ITGB4) occur frequently in the context of EMT and/or cancer." (PMID 36755019, 2023). "However, unlike COL20A1, COL17A1 is found in subsets of tumors in a number of cancers." (PMID 37414817, 2023).
genetic disorder (2 papers, 2022 to 2023). "COL17A1 mutations can also cause epithelial current erosion dystrophy, a genetic disorder characterized by corneal erosion." (PMID 37835579, 2023). "Junctional epidermolysis bullosa intermediate (JEB intermediate) is an autosomal recessive inherited disease that is associated with a series of gene variants, including those of COL17A1." (PMID 35717189, 2022).
COL17A1 also shares sentences with these, for which no sentence is quoted: Alzheimer disease (11 papers); autoimmune disease (11); Autoimmunity (11); mucous membrane pemphigoid (11); Erythema (10); pemphigoid gestationis (9); Pruritus (9); neurological disease (8); multiple sclerosis (7); Parkinson disease (7); dementia (6); eosinophilia (6); epidermolysis bullosa acquisita (6); non-small cell lung carcinoma (6); pemphigus (6); urticaria (6); COVID-19 (4); epithelial carcinoma (4); lichen planus (3); amelogenesis imperfecta (2); cutaneous squamous cell carcinoma (2); head and neck squamous cell carcinoma (2); inflammatory skin disease (2); lung squamous cell carcinoma (2); metastatic melanoma (2); Nail dystrophy (2); neurodegenerative disease (2); skin cancer (2); skin disorder (2); Stroke (2).
A further 69 diseases each share a sentence with COL17A1 in 1 paper.